IGF2BP3 (insulin like growth factor 2 mRNA binding protein 3)
Diseases named in the same sentence as IGF2BP3 in open-access papers (continued):
Sharing a sentence is not in itself a finding about the gene and the disease.
tumor (continued). "It has been shown that phenotypic attachment morphology and cell–cell adhesion are more prominent in tumour cells overexpressing IGF2BP3 in vitro than in cells with low expression of IGF2BP36; in vivo, overexpression of IGF2BP3 can increase tumour cell formation and metastasis." (PMID 38358034, 2024). "Nude mice implanted subcutaneously with CDDP-resistant T24 cells were injected intraperitoneally with CDDP (2 mg/kg) every 3 days for 35 days and the results demonstrated that SRD5A3 knockdown and IGF2BP3 knockdown effectively inhibited the tumor growth in subcutaneous implantation model." (PMID 39680264, 2024). "Five paired GC tumor and para-tumor tissues were collected to check the expressions of IGF2BP3." (PMID 38448411, 2024). "In addition, the IGF2BP3/tripartite motif containing 25 (TRIM25)/miR-3614 axis represents a new way to regulate tumor cell proliferation." (PMID 39054967, 2024). "However, this triggers an overall rise in m6A levels in infected tumor cells via the IGF2BP3/MIB1/FTO feedback loop, ultimately leading to CSF3-mediated NETosis." (PMID 38167409, 2024). "In a subcutaneous murine tumor model, lenvatinib provoked significant IGF2BP3 lactylation." (PMID 39450426, 2024). "moreover, compared with the control group, PCAT5 knockdown significantly reduce the average volume of xenografts in nude mice, and overexpression of IGF2BP3 could save tumor growth inhibition of PCAT5 knockdown." (PMID 38565547, 2024). "Also, the average methylation level of these sites negatively correlated with IGF2BP3 mRNA levels in most of the tumor types in TCGA datasets." (PMID 38504159, 2024). "Animal experiments showed that IGF2BP3 knockdown could effectively inhibited the tumor growth of xenografts generated from T24R cells with or without CDDP treatment." (PMID 39680264, 2024). "Furthermore, a subcutaneous tumorigenesis mouse model showed that IGF2BP3 KD inhibited in vivo xenograft tumor growth and mass of OE-19 cells, suggesting that IGF2BP3 KD can suppress tumor progression in AEG cancer." (PMID 39247830, 2024). "Many studies have shown that IGF2BP3 has a promoting role in the development of tumours." (PMID 38358034, 2024). "MKRN2 silencing promotes tumor proliferation and migration by decreasing ubiquitination of IGF2BP3." (PMID 38565547, 2024). "Furthermore, our pan-cancer analysis revealed that the methylation status of IGF2BP3 promoter negatively correlated with its expression in various tumor types, indicating that the methylation regulation of IGF2BP3 expression is also present in other tumors." (PMID 38504159, 2024). "Additionally, it has been observed that IGF2BP3 exhibits elevated expression levels in BC tumor samples." (PMID 39342406, 2024). "Moreover, we found that IGF2BP3 expression positively correlated with its copy number in 22 kinds of tumor through analyzing the multi-omics data of TCGA cohort." (PMID 38504159, 2024). "In conclusion, IGF2BP3 participated in the immune modulation of pan-cancer and may have potential to be a new immunotherapeutic target in the tumor therapy." (PMID 38577615, 2024). "In order to confirm the role of LIN28B, PCAT5, and IGF2BP3 in tumor growth in vivo, we subcutaneously injected Ishikawa or HEC-1A cells with knockdown of LIN28B, PCAT5 and IGF2BP3 respectively, or a combined knockdown of LIN28B + PCAT5 + IGF2BP3 to construct a xenograft tumor model in nude mice." (PMID 38565547, 2024). "Additionally, IGF2BP3, a modulator of the m6A enzyme, is upregulated and regulates the expression of programmed death ligand-1 (PD-L1) to increase the malignancy of tumor cells." (PMID 38992083, 2024). "In summary, multiple signalling pathways are involved in the promotion of tumour growth by IGF2BP3." (PMID 38358034, 2024). "IGF2BP3 could promote JAK/ Activation of the STAT pathway to inhibit tumor cell apoptosis and furtherance cell proliferation and cell cycle progression." (PMID 37505298, 2024).
tumor (continued). "Furthermore, it regulates tumorigenesis, cancer progression, tumor metastasis, and invasion, suggesting that IGF2BP3 is a promising target for cancer therapies." (PMID 37663284, 2023). "In addition, METTL3, YTHDF3 and IGF2BP3 affect tumor angiogenesis by regulating the expression of VEGF." (PMID 38053093, 2023). "Finally, in our current study of IGF2BP3 biological function, it was shown that IGF2BP3 presented significant participation in biological processes related to immune response and facilitated tumor development in various cancers." (PMID 36761737, 2023). "IGF2BP3 has demonstrated to the malignant transformation of tumor." (PMID 36761737, 2023). "The upregulaion of BIRC5 expression recognized and enhanced by IGF2BP3 could then promote the tumour’s progression, metastasis, and VEGFA-regulated angiogenesis." (PMID 37284313, 2023). "In addition, the regulatory mechanism of IGF2BP3 in the tumor microenvironment remains to be further studied." (PMID 37298373, 2023). "The inhibition of the lncRNA KCNMB2-AS1/miR-130b-5p/miR-4294/IGF2BP3 axis could retard tumor growth in vivo." (PMID 37298373, 2023). "In addition, a xenograft tumour model was established to further evaluate the effect of IGF2BP3 ubiquitination on tumourigenesis." (PMID 37877353, 2023). "Notably, silencing IGF2BP3 potently impaired the stemness properties in NPC cell lines and lung metastasis in tumors, and these effects were abrogated by NOTCH3 overexpression, suggesting that IGF2BP3 promotes tumor metastasis through Notch3 pathway." (PMID 37853162, 2023). "Although previous studies have reported that the behavior and prognosis of tumor patients may be influenced by immune infiltration, the interaction mechanism between ENO2, IGF2BP3, and the tumor microenvironment (TME) in CRC remains unclear." (PMID 37644235, 2023). "We next investigated whether circRNF10/ZBTB48/ IGF2BP3 feedback loop impacts GBM tumor burden in vivo." (PMID 37723588, 2023). "Among the RBPs, IGF2BP3 is of particular interest in tumorigenesis and tumor progression." (PMID 37658049, 2023). "Additionally, there is evidence that IGF2BP3 can interact with non-coding RNAs including miRNAs, lncRNAs and circRNAs to affect tumor progression." (PMID 37340423, 2023). "Considering the correlation between CAFs and tumor fibrosis, it remains to be determined whether IGF2BP3 expressed by fibroblasts has an effect on the biological behavior of tumor cells." (PMID 36450891, 2023). "We further assumed that IGF2BP3 may educate inflammatory tumor microenvironment to promote tumor progression by orchestrating crosstalk between tumor cells and their microenvironment." (PMID 36732736, 2023). "Tumor tissues were extracted for qRT-PCR analysis of linc01224, miR-485-5p and IGF2BP3." (PMID 37859812, 2023). "JQ1 123 and I-BET151 27, belonging to the bromodomain and extraterminal domain class of inhibitors, have been validated to downregulate IGF2BP3 expression and impair tumor growth in Ewing sarcoma and mixed-lineage leukemia-rearranged B-acute lymphoblastic leukemia." (PMID 37554271, 2023). "Here, we identified IGF2BP3 as a TGFβ-responsive circITGB6 interactor, whose depletion abolished the metastasis-promoting effect of circITGB6, consistent with the positive correlation between IGF2BP3 and tumor metastasis." (PMID 37898647, 2023). "Here, we identified circNFATC3 that bound to the IGF2BP3 protein, and was upregulated in GC tissues compared with non-tumor tissues and was positively associated with tumor volume." (PMID 37340423, 2023). "Arguably, to pigeon-hole either SESN2 or IGF2BP3 as either as oncogene or tumor suppressor is not overly helpful unless the underlying context is considered." (PMID 37059726, 2023). "Taken together, our results suggested that IGF2BP3 might promote tumor cell proliferation and tumorigenesis via activation of the EGFR signaling pathway." (PMID 37658049, 2023).
tumor (continued). "Therefore, combining the finding of these several studies shows that IGF2BP3 plays a tumor-promoting role." (PMID 37298373, 2023). "Likewise, MYC effectively activates the expression of IGF2BP3 by binding to its promoter to drive tumor progression and metastasis." (PMID 37554271, 2023). "The METTL3/IGF2BP3/HDGF axis promotes tumor angiogenesis, tumor growth, and liver metastasis." (PMID 37298373, 2023). "This study revealed that IGF2BP3 may play a role in the radiosensitivity of tumor cells; more researchers in the future can explore the role of IGF2BP3 in radiosensitization." (PMID 37298373, 2023). "Similarly, IGF2BP3 impairs anti-tumor immunity via PD-L1-mediated T cell activation, exhaustion, and infiltration in breast cancer." (PMID 37554271, 2023). "In addition, immunohistochemical validation suggested that IGF2BP3 staining appeared in fibroblasts surrounding the tumor tissue." (PMID 36450891, 2023). "IGF2BP3 upregulation contributed to markedly higher tumor incidence and faster xenograft outgrowth." (PMID 37853162, 2023). "Furthermore, GSI treatment and silencing NOTCH3 significantly abrogated IGF2BP3-mediated tumor-initiating ability." (PMID 37853162, 2023). "Additionally, IGF2BP3 upregulation has been observed in many cancer types 37-41, supporting tumor growth and metastasis." (PMID 37859812, 2023). "In addition, the phytochemicals isocorydine derivative and isoliquiritigenin inhibit the expression of IGF2BP3 to repress tumor cell proliferation." (PMID 37298373, 2023). "We next hypothesized that patients with CRC having higher IGF2BP3 expression would be more sensitive to anti-tumor drug candidates targeting IGF2BP3." (PMID 37658049, 2023). "Furthermore, the overexpression of IGF2BP3 dramatically increased tumor volumes in xenograft mouse models, whereas the knockout of IGF2BP3 effectively suppressed tumor growth." (PMID 37658049, 2023). "Analysis of tumor immune infiltration showed the elevated expression levels of IGF2BP3, DPCR1, HOXD10, TRIM7, and ZIC5 tended to be correlated with the increased tumor infiltrating B cells, CD8+ T cells, CD4+ T cells, and APCs including macrophages and DCs in COAD patients." (PMID 35593226, 2022). "Moreover, inhibition of METTL3 or IGF2BP3 enhanced anti-tumor immunity through PD-L1-mediated T cell activation, exhaustion, and infiltration both in vitro and in vivo." (PMID 35197058, 2022). "Moreover, METTL3/IGF2BP3 inhibition reduces the stabilization of PD-L1 mRNA, thus enhancing anti-tumor immunity through T-cell activation, exhaustion and infiltration." (PMID 36428700, 2022). "Interestingly, the METTL3/IGF2BP3 axis promotes tumor immune escape via m6A modification of PD-L1 mRNA and suppression of T cell activation in breast cancer." (PMID 35794625, 2022). "Thus, Igf2bp3 deletion significantly reduces tumor burden and attenuates disease severity in MLL-Af4 transplanted mice." (PMID 34321607, 2022). "Following the treatment indeed the silencing of METTL3 or IGF2BP3 could suppress tumor growth, tumor weight, and volume, similar to effects observed upon PD-L1 blockade treatment; PD-L1 overexpression was able to partially rescue tumor growth." (PMID 35197058, 2022). "Interestingly, IGF2BP3 is highly expressed in lung and breast cancers, where it regulates tumor occurrence and development." (PMID 36064747, 2022). "Moreover, an m6A regulator, IGF2BP3, was found to be highly expressed in the tumor samples, regulating both the total and membrane-bound PD-L1 expression levels." (PMID 35148766, 2022). "Furthermore, the tumor microenvironments of high- versus low-IGF2BP3 expression groups showed significant differences and IGF2BP3 predicted the efficiency of immunotherapy." (PMID 35677634, 2022). "Moreover, as observed in tumour cells, circNEIL3 increased IGF2BP3 protein expression and inhibited IGF2BP3 ubiquitination in differentiated THP1 macrophages." (PMID 35031058, 2022).
tumor (continued). "Moreover, similar to circNEIL3 enrichment analysis, the GSEA results also showed that classical pathways involved in tumour pathogenesis were significantly enriched in the high IGF2BP3 expression group in the CGGA and TCGA datasets." (PMID 35031058, 2022). "Among RBPs, IGF2BP3 is particularly important in tumorigenesis and tumour progression." (PMID 33637103, 2021). "Also, the knowledge of the interaction between IGF2BP3 and tumor hypoxic microenvironment is quite limited." (PMID 34621671, 2021). "The results revealed that IGF2BP3, RBM15B, and METTL16 mutations may be potential biomarkers for certain anti-tumor therapies." (PMID 34446007, 2021). "Moreover, western blot assay showed that IGF2BP3 protein expression level was notably increased in 6 SC tumor tissues compared to matched adjacent normal tissues." (PMID 34621671, 2021). "These conclusions are urging us to carry out relevant research to verify whether inhibiting the expression of IGF2BP2 and IGF2BP3 can inhibit the growth of the tumor." (PMID 33628845, 2021). "T3 + T4 tumours, III + IV tumours, and N1 tumours had higher expression levels of IGF2BP3." (PMID 33637103, 2021). "A deep insight into the complex interactions between IGF2BP3 and tumor hypoxic microenvironment or its m6A-dependent targets might contribute to the clinical use of IGF2BP3." (PMID 34621671, 2021). "High expression of IGF2BP3 was observed in the tumour cells of 65% of the patients." (PMID 33094561, 2020). "Similarly, both of our results confirmed the role of IGF2BP2 and IGF2BP3 in inhibiting tumour progression." (PMID 33246429, 2020). "Subsequent studies have also found a high expression of IGF2BP3 in various tumor types." (PMID 32121275, 2020). "We found that the copy number loss of ZC3H13, FTO, YTHDC2, WTAP and ALKBH5 decreased the protein expression in tumor samples, and meanwhile, patients with amplification of IGF2BP3, HNRNPA2B1 and IGF2BP2 presented higher expression level of these three proteins than normal tissues." (PMID 32710725, 2020). "Because CXCR4 is induced in EWS cells exposed to hypoxia, a common condition of human tumor microenvironment, we investigated the contribution of the IGF2BP3/CD164/CXCR4 axis on CXCL12-evoked biological responses of EWS cells under normoxic (21% O2) or hypoxic conditions (1% O2)." (PMID 32719743, 2020). "IGF2BP3 was wildly overexpressed in various cancer and worked as a pan-cancer tumor marker." (PMID 32993738, 2020). "Tumour growth of IGF2BP3 silenced cells was slower than that of the vector‐transfected cells." (PMID 33094561, 2020). "Tumour growth in vivo was also suppressed by knocking down of IGF2BP3." (PMID 33094561, 2020). "Notably, both IGF2BP3 and PDPN expression was shown to correlate with lymph node metastasis in OSCC patients and IGF2BP3 downregulation inhibited invadopodia formation, extracellular matrix degradation, and tumor growth and invasiveness." (PMID 32957697, 2020). "In addition, by upregulating LIN28, which also enhances the expression of IGF2, histone H2a, cyclin A, cyclin B, and CDK4, IGF2BP3 can establish complex, positive-feedback loops that further facilitate tumor cell growth and malignancy." (PMID 32010687, 2019). "Ectopic expression of IGF2BP3 enhances tumor cell aggressiveness in transgenic animals." (PMID 31440515, 2019). "At posttranscriptional level, several miRNAs regulate IGF2BP3 in different tumor types." (PMID 32010687, 2019). "IGF2BP3 represents an intriguing posttranscriptional factor in tumor malignancy." (PMID 32010687, 2019). "In addition, interactions between IGF2BP3 and the tumor-microenvironment have been identified, highlighting a novel putative function in the interplay between tumor and normal cells." (PMID 32010687, 2019).
tumor (continued). "Compared to the phenotype of IGF2BP3-null cells, IGF2BP3-expressing tumor cells display a marked motility-prone phenotype with an adherent shape, cellular extensions, lamellipodia, frequent cell–cell adhesion contacts and an increased capability to form metastases in vivo." (PMID 32010687, 2019). "The interaction between IGF2BP3 and the tumor microenvironment is still poorly described." (PMID 32010687, 2019). "We also demonstrated that IGF2BP3 inhibition led to reduced tumor growth in vivo." (PMID 32083017, 2019). "Also, in vitro studies have shown that IGF2BP3 promotes tumor cell survival, proliferation, anchorage-independent growth, chemoresistance migration and invasiveness." (PMID 31440515, 2019). "As previous reports also reported that other upregulated cell cycle-related genes show promoter demethylation besides IGF2BP3, DNA demethylation may be part of the mechanism that promotes tumor progression." (PMID 30760837, 2019). "Previously, the tumor-promoting activity of IGF2BP3 was focused on its mRNA activity." (PMID 29212181, 2017). "Thus, the pro-survival role of IGF2BP1 and IGF2BP3 in response to these therapeutic treatments in vitro suggests that IGF2BPs also serve a role in mediating chemo-/radio-resistance of tumor cells." (PMID 23069990, 2013). "IGF2BP3 expression differed between tumor grade (P < 0.001, Pearson's Chi-square)." (PMID 20178612, 2010). "Notably, IGF2BP3 was highly expressed within the xenograft tumor tissues." (PMID 40083693, 2025). "In addition, IGF2BP3 promotes tumor immune escape by modulating immune cell presence in the TME." (PMID 40801655, 2025). "We identified 281 direct RNA targets of IGF2BP3 with enriched functions linked to metastasis-related processes, and several targets overlapped with genes differentially expressed between MCC primary tumors and metastases, implying that IGF2BP3 and its targets contribute to tumor progression." (PMID 40162116, 2025). "Therapeutic targeting of this axis is supported by preclinical evidence: combined LINC01559 silencing and osimertinib treatment cooperatively suppressed tumor growth in xenografts, suggesting that disrupting IGF2BP3’s RNA-stabilizing activity could re-sensitize resistant tumors." (PMID 40313617, 2025). "Moreover, many experiments have indicated that IGF2BP3 has a role in promoting or maintaining tumour cell subsets with stem cell characteristics and is a contributing factor in the establishment and progression of tumours." (PMID 38358034, 2024). "Notably, we also identify inter-tumor heterogeneity of OS RNA interactomes with more aggressive tumors showing translation addiction and exquisite vulnerability for translation inhibition, as well as induction of an IGF2BP3-Myc positive feedback loop." (PMID 38561347, 2024). "Finally, our in vivo study showed that knockdown of LIN28B, PCAT5, and IGF2BP3 could inhibit tumor growth in xenografted tumors, and mice injected with the combination of these three agents showed minimal xenografted tumor volume and weight." (PMID 38565547, 2024). "Moreover, mRNA levels of IGF2BP3 also increased in multiple different kinds of tumor, indicating that IGF2BP3 may harbor as potential oncogene across multiple cancer types." (PMID 38448411, 2024). "Interestingly, the effect was more pronounced in tumor cells overexpressing IGF2BP3." (PMID 38167409, 2024). "Thus, IGF2BP3 may represent a promising biomarker related to tumor immune cell infiltration, and it provides a possible regimen of immune-related therapies for many cancers." (PMID 36761737, 2023). "In addition, we examined the expression levels of IGF2BP3 across various tumor types." (PMID 36761737, 2023). "Therefore, the elevated expression of ENO2 and IGF2BP3 in CRC may influence tumor immunity and contribute to carcinogenesis, providing implications for future research on immunotherapy." (PMID 37644235, 2023).